TIMELESS (timeless circadian regulator)
Diseases named in the same sentence as TIMELESS in open-access papers (continued):
Sharing a sentence is not in itself a finding about the gene and the disease.
ovarian carcinoma (continued). "To confirm the function of TIMELESS in MEX3A-mediated proliferation, migration, and invasion of ovarian cancer cells, we transiently transfected TIMELESS siRNA into HEY cells overexpressing MEX3A." (PMID 35715407, 2022). "The results of this paper demonstrated that the MEX3A/TIMELESS signaling pathway was a key regulator of ovarian cancer, and MEX3A was a novel possible treatment target for ovarian cancer patients." (PMID 35715407, 2022). "Therefore, TIMELESS is the main target that mediates the role of MEX3A in the growth and metastasis of ovarian cancer cells." (PMID 35715407, 2022).
cervical carcinoma (4 papers, 2013 to 2023). A carcinoma arising from either the exocervical squamous epithelium or the endocervical glandular epithelium. "According to a study on cervical cancer, TIMELESS overexpression is associated with lymphovascular space involvement, pelvic lymph node metastases, and worse OS and DFS." (PMID 38053143, 2023). "We observed that TIMELESS expression in invasive cervical cancer tissue was significantly higher than in normal tissue (P < 0.001) and preinvasive cervical cancer tissue (P < 0.001)." (PMID 24161199, 2013). "Interestingly, TIMELESS has been shown to be required for the maintenance of cancer-associated viral genomes as well, which could provide some rationale for its particularly high expression in cervical cancer that is almost always driven by human papillomavirus (HPV)." (PMID 30629587, 2019). "It is also likely that TIMELESS expression is increased through other mechanisms since TIMELESS is overexpressed, at least at the mRNA level, in several cancers that are not commonly driven by oncogenic Ras including breast, uterine, ovarian, and cervical cancers." (PMID 30629587, 2019).
colon cancer (4 papers, 2016 to 2022). "In a panel of five colon cancer cell lines, RNAi-mediated TIMELESS depletion for 72 hours ubiquitously caused an increase in γH2AX, a marker of DNA damage; however, the cell lines demonstrated variable levels of H2AX phosphorylation with HCT15 cells resulting in a relatively small increase." (PMID 30629587, 2019). "Further validation showed that, in a panel of colon cancer cell lines, TIMELESS mRNA and protein expressions were significantly upregulated compared to HCECs." (PMID 33120942, 2020). "Cell viability was also markedly reliant on TIMELESS expression in colon cancer cells compared to HCECs, similar to that of KSR1." (PMID 33120942, 2020). "In contrast, TIMELESS depletion in combination with Wee1 or CHK1 inhibition further decreased cell metabolic capacity than either perturbation alone in all the colon cancer cell lines tested except for HCT15 cells." (PMID 30629587, 2019). "This study demonstrates that TIMELESS is overexpressed in colon cancer cells at least in part due to increased ERK signaling in cancer." (PMID 30629587, 2019). "This was further corroborated in a series of human colon cancer cell lines in which miR-139-5p induced TIMELESS down-modulation, determining the cell phenotype." (PMID 27323779, 2016). "Decreased viability was shown to be due to the induction of a G2/M cell cycle arrest via CHK1 phosphorylation, revealing TIMELESS as a potential target for colon cancer therapy, particularly in combination with other DNA damaging agents or CHK1/Wee1 inhibition." (PMID 33120942, 2020). "However, in colon cancer cells, TIMELESS is highly overexpressed throughout the entirety of the 24-h cycle." (PMID 33120942, 2020). "Despite the potential for some cancer cells to be insensitive or develop insensitivity to TIMELESS depletion, four of the colon cancer cell lines that were tested in this study demonstrated a substantial requirement for TIMELESS in order to maintain a high level of proliferation." (PMID 30629587, 2019). "Further evaluation showed that, in colon cancer HCT116 cells, activated ERK promoted TIMELESS expression." (PMID 33120942, 2020). "Five colon cancer cells, HCT116, HCT15, SW480, SW620, and RKO depleted of TIMELESS had a significant decrease in cell survival and proliferation." (PMID 33120942, 2020). "In a panel of human colon cancer cell lines (HCT116, HCT15, SW480, SW620, RKO, LoVo, and T84), TIMELESS is upregulated at the mRNA and protein level compared to HCECs." (PMID 30629587, 2019). "TIMELESS depletion reduced metabolic capacity based on the alamarBlue viability assay in multiple colon cancer cell lines; however, TIMELESS depletion did not significantly increase apoptosis based on very little, if any, increase in PARP cleavage." (PMID 30629587, 2019). "HCECs expressing exogenous RasG12V have increased TIMELESS expression relative to HCECs albeit not to the levels seen in the colon cancer cell lines tested." (PMID 30629587, 2019). "In other colon cancer cell lines where ERK inhibition did not affect TIMELESS levels, mTOR inhibition reduced TIMELESS mRNA translation efficiency and protein expression." (PMID 33120942, 2020).
glioma (4 papers, 2021 to 2023). A benign or malignant brain and spinal cord tumor that arises from glial cells (astrocytes, oligodendrocytes, ependymal cells). "The differential expression of CCGs in glioma grading confirmed that cluster I genes (ARNRL, NPAS2, and TIMELESS) and CRY1, with cluster II genes (CRY2, DBP, NR1D1, NR1D2, PER2, PER3, and RORA) showed significantly opposite expression trends in brain tissues." (PMID 35832846, 2022). "Recent work from Wang and Chen (2018) evidenced that TIMELESS is overexpressed in high-grade gliomas compared to low-grade glioma and non-pathological tissues." (PMID 34361055, 2021). "Besides, the expression of eight CCGs (CRY2, DBP, NR1D1, NR1D2, PER2, PER3, RORA, and TIMELESS) was negatively regulated by methylation and positively regulated by CNV in glioma, which is consisting with previous studies that DNA methylation and CNV can promote abnormal gene expression." (PMID 35832846, 2022).
liver cancer (4 papers, 2020 to 2023). An epithelial or non-epithelial malignant neoplasm that arises from the liver. "Knockout or inhibition of TIMELESS can lead to cell cycle stagnation and subsequent apoptosis, which limits the growth of liver cancer cells." (PMID 34285836, 2021). "As shown in pancancer analysis or liver cancer analysis, Cluster 1 and TIMELESS exerted opposite effects on the same signaling pathway; that is, Cluster 1 activated, whereas TIMELESS inhibited the same pathway and vice versa." (PMID 34745328, 2021). "It was observed that higher expression of Cluster 1 might enhance the chemoresistance of these anticancer reagents, implying that inhibition of Cluster 1, or activation of TIMELESS, may render liver cancer cells more sensitive to chemotherapy." (PMID 34745328, 2021).
lung adenocarcinoma (3 papers, 2024 to 2026). A carcinoma that arises from the lung and is characterized by the presence of malignant glandular epithelial cells. "The present study aimed to elucidate the molecular network governed by the highly expressed RBP TIMELESS in lung adenocarcinoma (LUAD) and determine its mechanistic role in LUAD progression." (PMID 41641368, 2026). "Noncoding RNAs (ncRNAs) regulating overexpression of TIMELESS in lung adenocarcinoma (LUAD) were explored with expression, correlation, and survival analyses." (PMID 38261568, 2024).
melanoma (3 papers, 2021 to 2025). A malignant, usually aggressive tumor composed of atypical, neoplastic melanocytes. "have specifically noted that TIMELESS may regulate DNA replication and cell cycle-related genes, potentially influencing melanoma progression." (PMID 40191195, 2025).
schizophrenia (3 papers, 2010 to 2019). A major psychotic disorder characterized by abnormalities in the perception or expression of reality. "Associations between circadian gene polymorphisms, including TIMELESS, and some mental disorders have been found, including schizophrenia." (PMID 21070662, 2010). "Earlier studies have also revealed a role for TIMELESS in insomnia, mania, bipolar disorder type 1, schizophrenia, and schizoaffective disorder." (PMID 20174623, 2010). "Furthermore, in our analysis, several DE miRNA targets were found to be associated with neuropsychiatric disorders, such as schizophrenia (TTN, SYNPO), depressive disorder (PPARGC1B, TIMELESS), and autism (TAF1, TRIO)." (PMID 31652596, 2019). "For similar reasons, we expected that also the link between latitude and schizophrenia cannot be completely explained by vitamin D. For example, in the intersection between LRGs and genes related with schizophrenia there is a gene involved in the circadian rhythms, TIMELESS." (PMID 21070662, 2010).
bipolar disorder (2 papers, 2022 to 2024). A disorder of the brain that causes unusual shifts in mood, energy, activity levels and the ability to carry out day-to-day tasks. "Previous research has shown that mutations in the clock genes, specifically the timeless homolog gene (TIMELESS) and the period homolog 3 gene (PER3), are linked to mental health conditions such as schizophrenia and bipolar disorder." (PMID 39584972, 2024). "In particular, Benach and colleagues investigated the possible link among polymorphisms of CLOCK, ARNTL, TIMELESS, and PER3 genes (complex analysis of single polymorphisms and haplotypes–SNP interactions) and the comorbidity of alcohol abuse (AAD) in bipolar disorder patients." (PMID 35893041, 2022).
depression (2 papers, 2010 to 2019). "Thus, we obtained strong evidence of a role for TIMELESS in the genetic background of depression with signs of sleep disturbance in both genders, but the associated alleles were not the same." (PMID 20174623, 2010).
prostate carcinoma (2 papers, 2013 to 2024). A carcinoma that arises from epithelial cells of the prostate gland. "A body of evidence highlights that the circadian gene TIMELESS is notably upregulated in various cancers, including breast, cervical, nasopharyngeal, and prostate cancers, where its elevated expression is linked to enhanced tumor growth." (PMID 38178094, 2024). "Moreover, TIMELESS has been implicated in the development and progression of various other cancers, including nasopharyngeal carcinoma, prostate cancer, lung cancer, colorectal cancer, and kidney cancer." (PMID 38178094, 2024).
childhood asthma (1 paper, 2023). "Although it does not belong to the seven core clock genes, the timeless circadian regulator TIMELESS has been reported to be associated with childhood asthma." (PMID 37108640, 2023).
COVID-19 (1 paper, 2022). A disease caused by infection with severe acute respiratory syndrome coronavirus 2. "Interference with TIMELESS and other genes associated with it to regulate autoantibody expression may be a potential strategy for immunotherapy against thrombogenesis in severe COVID-19 patients." (PMID 36241659, 2022). "We found that TIMELESS was the only common DEG presented in the hub genes, suggesting an important role of TIMELESS in the pathogenesis of both COVID-19 and APS." (PMID 36241659, 2022). "Combined with the role of TIMELESS in the production of aPLs, and data from our previous studies, we speculated that TIMELESS played a potential role in regulating the thrombotic phenotype in COVID-19 patients." (PMID 36241659, 2022). "Functional analyses using gene ontology terms and the Kyoto Encyclopedia of Genes and Genomes pathway suggested that TIMELESS might contribute to the production of antiphospholipid antibody and thrombosis in both COVID-19 and APS patients." (PMID 36241659, 2022). "During the investigation of the role of TIMELESS in APS and COVID-19, we found that several proteins involved in the regulation of autophagy were also present in the PPI networks." (PMID 36241659, 2022).
Fanconi anemia (1 paper, 2025). Fanconi anemia (FA) is a hereditary DNA repair disorder characterized by progressive pancytopenia with bone marrow failure, variable congenital malformations and predisposition to develop hematological or solid tumors. "TIMELESS also contributes to DNA stability during replication, with the pathway analysis highlighting the Fanconi anemia pathway, associated with medulloblastoma risk." (PMID 40002179, 2025).
kidney cancer (1 paper, 2022). Primary or metastatic malignant neoplasm involving the kidney. "TIMELESS expression was upregulated significantly in most cancer types (P < 0.05), while it was downregulated in kidney cancer (KICH and KIRC)." (PMID 35078435, 2022).
lung squamous cell carcinoma (1 paper, 2022). "For instance, circ-TIMELESS via the miR‐136‐5p/ROCK1 axis could regulate proliferation of lung squamous cell carcinoma cells." (PMID 36177350, 2022).
mesothelioma (1 paper, 2009). A usually malignant and aggressive neoplasm of the mesothelium which is often associated with exposure to asbestos. "TIMELESS was also overexpressed in the mesothelioma samples." (PMID 19662092, 2009).
mucopolysaccharidosis type 2 (1 paper, 2013). A lysosomal storage disease leading to a massive accumulation of glycosaminoglycans and a wide variety of symptoms including distinctive coarse facial features, short stature, cardio-respiratory involvement and skeletal abnormalities. "After 24 hours of treatment with idursulfase in fibroblasts of patients with Mucopolysaccharidosis type II the expression evaluated by NGS of the genes CLOCK, ARNTL2, NR1D1, NR1D2, and TIMELESS showed higher expression levels compared to untreated HS fibroblasts." (PMID 24083598, 2013).
pancreatic cancer (1 paper, 2019). "Another mechanism showing promise in pancreatic cancer treatment might be TIMELESS, involved in DNA damage response, whose expression was found to be altered in pancreatic cancer." (PMID 31379749, 2019).
renal cell carcinoma (1 paper, 2020). "In recent years, it has been found that the expression of TIMELESS in tumors is not completely uniform: it is weakly expressed in renal cell carcinoma, ductal cell carcinoma of the pancreas and other malignant tumors and is closely related to poor patient survival." (PMID 32528520, 2020).
cancer (28 papers, 2013 to 2025). A tumor composed of atypical neoplastic, often pleomorphic cells that invade other tissues. "The over-expression of TIMELESS is linked to poor prognosis in various cancers and has been suggested as a therapeutic target." (PMID 40002179, 2025). "In this study, we investigated the expression of TIMELESS and its association with survival across several types of human cancer using data from The Cancer Genome Atlas (TCGA) and the Genotype-Tissue Expression Program." (PMID 38261568, 2024). "The gene TIMELESS, which is involved in the circadian clock and the cell cycle, has recently been linked to various human cancers." (PMID 38053143, 2023). "The seven DEGs (AURKA, BUB1, CDC6, MAD2L1, NDC80, ZWINT, and TIMELESS) coexpressed only in the LC&OC coexpression network have been associated with the acquisition of the hallmarks of cancer." (PMID 36101460, 2022). "Among these rhythm genes, PER1, PER2, PER3, and TIMELESS are the most frequently mutated genes in pan‐cancer." (PMID 31927791, 2020). "Our results suggest a potential role for TIMELESS in tumorigenesis, which warrants further investigation of TIMELESS expression as a potential biomarker of cancer susceptibility and prognostic outcome." (PMID 24161199, 2013). "Circadian genes such as TIMELESS have been associated with several pathologies, including cancer." (PMID 38261568, 2024). "Likewise, our study showed that TIMELESS was significantly associated with the CAF in various cancer, including ACC, ESCA, HNSC, LGG, MESO, UVM, STAD, and TGCT." (PMID 38053143, 2023). "Nevertheless, the association between TIMELESS expression and the prognosis of individuals afflicted with pan-cancer remains largely unknown." (PMID 38053143, 2023). "To explore TIMELESS’s potential functional significance in regulating cancer-relevant gene networks, we performed a loss-of-function analysis using TIMELESS-targeting siRNA oligos, followed by a whole genome expression microarray and subsequent network analysis." (PMID 24161199, 2013). "Similarly, in cervical cancer, TIMELESS overexpression is associated with a higher risk of recurrence and poorer recurrence-free survival rates, suggesting its potential as an independent prognostic marker in the early stages of this cancer." (PMID 38178094, 2024). "In summary, this study identified TIMELESS as a potential oncogene across multiple cancers, including LUAD." (PMID 38261568, 2024). "Several studies have highlighted the prominent expression of the TIMELESS gene in various cancer types." (PMID 38178094, 2024). "Some of these genes, such as MAPK, NOS2, CDK2, and TIMELESS, have been previously associated with VIP in non-cancer models." (PMID 37444395, 2023). "This study provides new insights into the link between the circadian gene TIMELESS and the development of various malignant tumors." (PMID 38053143, 2023). "Our study found that TIMELESS was aberrantly expressed and related to poorer survival in various malignant tumors, such as ACC, LGG, LIHC, and SARC." (PMID 38053143, 2023). "Using the BioGPS database, we looked into the expression of TIMELESS in several cancer cell lines as well as normal tissues, and we discovered that TIMELESS was highly expressed in practically all cancer cell lines." (PMID 38053143, 2023). "Pan-cancer single nucleotide variation analysis showed that the overall average mutation frequency ranged from 0 to 8.2%, and CRGs including AUTS2, TIMELESS, REV1, and PER2 showed high mutation frequencies." (PMID 36895015, 2023). "We succeeded in finding relatively new co-expressed genes, such as TIMELESS, IDUA, CPZ, MGC27165, C10orf56 and so on that were found to be associated with BC or other cancers until this decade." (PMID 33790307, 2021). "Among them, certain rhythm genes such as DBP, CRY2, and CIART are protective effectors for the prognosis of most cancers, whereas certain rhythm genes such as TIMELESS and SERPINE1 are risk factors for the prognosis of most cancer." (PMID 31927791, 2020).